EI24 (EI24 autophagy associated transmembrane protein)
Description:
Regulates formation of degradative autolysosomes during autophagy (By similarity).
Synonyms: PIG8; TP53I8; EPG4
Tractability: Antibody: UniProt predicts a signal peptide or a membrane-spanning region. PROTAC: ubiquitination databases record sites on it; its protein half-life has been measured.
Gene: Protein-coding gene on chromosome 11 (125,568,248 to 125,584,690, forward strand). Ensembl gene ENSG00000149547.
Subcellular location: Nucleus membrane; Cytoplasm; Endoplasmic reticulum membrane
Subcellular location (Human Protein Atlas): Cytosol; Endoplasmic reticulum; Golgi apparatus
Gene Ontology:
Molecular function: importin-alpha family protein binding; protein binding
Biological process: negative regulation of cell growth; apoptotic process; macroautophagy
Cellular component: cytosol; membrane; endoplasmic reticulum; cytoplasm; endoplasmic reticulum membrane; nuclear membrane
Genetic constraint (gnomAD): Loss-of-function variants: 17 observed, 35.3 expected, observed/expected ratio (o/e) 0.48, 90% interval 0.33 to 0.72. The upper end of that interval is the gene's LOEUF score, 0.72, which puts it in group 2 of 6, group 1 being the genes least tolerant of losing a copy. Missense variants: 252 observed, 340.84 expected, observed/expected ratio (o/e) 0.74, 90% interval 0.67 to 0.82. Synonymous variants: 105 observed, 128.39 expected, observed/expected ratio (o/e) 0.82, 90% interval 0.7 to 0.96.
Homologues: Orthologues: chimpanzee EI24 (99% identical), rabbit EI24 (99% identical), dog EI24 (99% identical), macaque EI24 (99% identical), mouse Ei24 (98% identical), rat Ei24 (98% identical), guinea pig EI24 (95% identical), tropical clawed frog ei24 (90% identical), pig EI24 (89% identical), zebrafish ei24 (81% identical), Drosophila melanogaster tank (43% identical), Caenorhabditis elegans epg-4 (27% identical).
Diseases named in the same sentence as EI24 in open-access papers:
EI24 is named in the same sentence as 31 diseases in open-access papers, as found by Europe PMC text mining. Sharing a sentence is not in itself a finding about the gene and the disease. The quoted sentences say what the papers report.
breast carcinoma (7 papers, 2011 to 2025). "Furthermore, the EI24 has found to be highly mutated in the case of aggressive breast cancer and is rather associated to tumour invasiveness than development of the primary tumour." (PMID 25496518, 2014). "Similarly, Ei24 is found in a region that shows frequent loss-of-heterozygosity in solid tumors, and its loss has been associated with increased breast cancer invasiveness." (PMID 21573140, 2011). "EI24 was located in cytoplasm, and there was a weak or negative EI24 staining in TNBC tissues bearing overexpressed miR-455-3p, whereas there was a diffuse and strong EI24 expression in HR positive breast cancer with low miR-455-3p expression (p<0.05)." (PMID 28038450, 2017). "EI24 mRNA level was lower in TNBC tissues than that in HR positive breast cancer using qRT-PCR assays." (PMID 28038450, 2017). "Although the current study primarily included melanoma and breast cancers, we also observed decreased EI24 expression in clinical datasets of metastatic ovarian, prostate, and colorectal cancers." (PMID 24280371, 2013). "In breast cancer, EI24 is a novel Bcl-2 binding protein which may contribute to apoptosis and low invasiveness by modulating the activity and/or function of Bcl-2." (PMID 28038450, 2017). "A similar effect of EI24 overexpression was observed in breast cancer 4T1 cells." (PMID 24280371, 2013). "Furthermore, EI24 expression correlated negatively with the progression stage of breast cancer measured using the Elston-Ellis grading system." (PMID 24280371, 2013). "In addition, knockdown of Ei24 in mouse fibroblasts or human breast cancer cell lines leads to increased resistance against etoposide-induced apoptosis." (PMID 21573140, 2011). "The chromosome 11 interval containing the EI24 and CHEK1 genes is a frequently altered region in breast cancer." (PMID 23844225, 2013). "We also examined the EI24 expression in TNBC and HR positive breast cancer tissue." (PMID 28038450, 2017). "With this tumor prosurvival role, EI24 and ASS1 both showed poor prognostic value in patients, not only in a same breast cancer dataset, but also across various cancer types." (PMID 40253325, 2025).
pancreatic cancer (4 papers, 2018 to 2022). "In this study, we clarified that loss of EI24 impaired autophagy and inhibited proliferation in pancreatic cancer cells, which are dependent on autophagy." (PMID 31396480, 2019). "The autophagy dependency of pancreatic cancer cells may lead to inhibition of cell proliferation after loss of autophagic components, such as EI24 and ATG5." (PMID 31396480, 2019). "EI24 deficiency in pancreatic tumor cell lines inhibited cell proliferation." (PMID 31396480, 2019). "Although the initial loss of EI24 and the associated loss of autophagy activity may have contributed to tumorigenesis, loss of EI24 at later stages impairs proliferation and cell survival in pancreatic cancer cells." (PMID 32878084, 2020). "Next, we determined whether EI24 deficiency leads to impaired pancreatic cancer cell growth." (PMID 31396480, 2019). "EI24 acts as a tumor suppressor gene in breast and cervical cancer cells, but it appears to play a different role in pancreatic cancer cells based on these results." (PMID 31396480, 2019). "We suggest that EI24, despite being a tumor suppressor, also acts as a tumor promoter in pancreatic cancer cells." (PMID 31396480, 2019). "EI24 has been reported as a tumor suppressor even in pancreatic cancer cells, which is in conflict with our observations." (PMID 31396480, 2019). "Here, we demonstrated that knockdown of EI24 using siRNA in pancreatic tumor cells led to impaired autophagy at a late step (increase in LC3-II and accumulation of p62 and autolysosomes)." (PMID 31396480, 2019). "We investigated the role of EI24 as a component of autophagy in pancreatic tumor cell proliferation." (PMID 31396480, 2019). "Our study demonstrated that enhanced expression of EI24 activates autophagy in vitro and in vivo in pancreatic cancer cells." (PMID 30369947, 2018). "High expression of EI24 was detected in 13 (36.11%) pancreatic cancer cases, while low expression was observed in 23 cases (63.89%) compared with adjacent normal tissues." (PMID 30369947, 2018). "Together, these results indicated that EI24 overexpression inhibited pancreatic cancer cell growth, induced cell cycle arrest in S phase, and attenuated cancer cell colony formation." (PMID 30369947, 2018). "Our results suggest that the overexpression of EI24 affected tumorigenesis in pancreatic cancer by inducing autophagy, resulting in the downregulation of c-Myc and suppression of proliferation, as well as causing cell cycle arrest." (PMID 30369947, 2018). "To examine the function of EI24 on pancreatic cancer tumorigenesis in vivo, we performed tumor formation assays in Balb/c nude mice." (PMID 30369947, 2018). "Therefore, further analysis of the data and execution of more comprehensive studies are required to clarify the detailed role of EI24 in pancreatic cancer carcinogenesis." (PMID 35508982, 2022). "However, in this study, EI24 appeared to play a different role in pancreatic cancer cells, suggesting varying roles depending on the cellular context." (PMID 31396480, 2019). "In conclusion, we suggest that EI24, as a component of autophagy, may promote pancreatic cancer cell growth." (PMID 31396480, 2019). "Taken together, our results suggest that EI24 acts as a tumor promoter in pancreatic tumor cells, and studying the role of EI24 in reference to its cellular context may lead to a useful therapeutic target." (PMID 31396480, 2019). "In this study, we examined the autophagic process and cell proliferation of EI24-deficient pancreatic tumor cells and compared the results with other organ-derived cells whose growth is not expected to be affected by EI24 deficiency." (PMID 31396480, 2019). "We wondered if the Beclin-1/p62/c-Myc signaling pathway is activated and functions in pancreatic cancer and whether EI24 plays a role in this pathway." (PMID 30369947, 2018).
pancreatic cancer (continued). "They found that knockdown (KD) or KO of EI24 utilizing siRNA or CRISPR/Cas9, respectively, impaired pancreatic cancer autophagy and then suppressed cell proliferation." (PMID 35508982, 2022). "Taken together, EI24 overexpression in pancreatic cancer cells did not activate autophagy process and then did not raise cell proliferation." (PMID 31396480, 2019). "In this study, EI24 deficiency did not affect cell proliferation in HCT116, colon cancer, HeLa, or U2OS cells, unlike in pancreatic cancer cells." (PMID 31396480, 2019). "In addition, the role of EI24 as an autophagy factor in pancreatic tumor cells has not yet been clarified." (PMID 31396480, 2019). "Thus, the net function of EI24 in pancreatic tumor cells is not clear due to its known tumor suppressor and possible tumor promoter functions." (PMID 31396480, 2019).
colon cancer (2 papers, 2011 to 2019).
esophageal squamous cell carcinoma (2 papers, 2017 to 2020). Esophageal squamous cell carcinoma (ESCC) is a type of esophageal carcinoma (EC) that can affect any part of the esophagus, but is usually located in the upper or middle third. "Similarly, a recent study showed miR-483-3p plays an oncogenic role in esophageal squamous cell carcinoma by targeting EI24." (PMID 28038450, 2017).
melanoma (2 papers, 2013 to 2019). A malignant, usually aggressive tumor composed of atypical, neoplastic melanocytes. "The function of EI24 has been investigated most thoroughly in breast, cervical, and melanoma cells." (PMID 31396480, 2019).
alcohol (1 paper, 2016). "Although the mechanisms of how tank/Ei24 regulates basal autophagy and ethanol sensitivity are not known, we were wondering whether Atg16 has a role in alcohol resistance." (PMID 27708416, 2016).
cervical cancer (1 paper, 2019). A primary or metastatic malignant neoplasm involving the cervix. "Based on these findings, EI24 may function as a tumor suppressor gene in breast and cervical cancers." (PMID 31396480, 2019).
diabetes (1 paper, 2025). "Ei24 TG mice also demonstrated resistance to high-dose STZ-induced diabetes." (PMID 40556865, 2025). "To test this hypothesis, we investigated the impact of Ei24 overexpression in mitigating streptozotocin (STZ)-induced diabetes, which mimics β-cell destruction." (PMID 40556865, 2025). "Ei24 transgenic (TG) mice were generated to assess the effects of Ei24 overexpression on aging, glucose homeostasis, and resistance to streptozotocin (STZ)-induced diabetes." (PMID 40556865, 2025).
invasive breast carcinoma (1 paper, 2013). A carcinoma that infiltrates the breast parenchyma. "We also detected loss of EI24 copy number in the most common types of invasive breast cancer, such as IDC, ILC, and mixed ductal/lobular carcinoma (IDLC), in the TCGA database." (PMID 24280371, 2013). "The Gluck breast dataset showed markedly reduced EI24 mRNA expression in invasive breast carcinomas compared with that in normal breast tissues." (PMID 24280371, 2013).
invasive ductal breast carcinoma (1 paper, 2013). The most common type of invasive breast carcinoma, accounting for approximately 70% of breast carcinomas. "In a dataset from The Cancer Genome Atlas (TCGA), EI24 expression was downregulated in invasive ductal breast carcinomas (IDCs) and invasive lobular breast carcinomas (ILCs) compared with normal breast samples." (PMID 24280371, 2013).
liposarcoma (1 paper, 2020). A usually painless malignant tumor that arises from adipose tissue. "In dedifferentiated liposarcoma and osteosarcoma, EI24 also exhibits a decreased expression level, implying that EI24 could serve as a tumor repressor gene." (PMID 32974192, 2020).
liver fibrosis (1 paper, 2025). "Studies have also shown that hUC-MSCs and their exosomes alleviate lipid deposition and liver fibrosis in MASH mice through mechanisms involving the upregulation of Etoposide-Induced gene 24 (EI24) protein and AMPK/mTOR signaling as well as activation of autophagy." (PMID 40129979, 2025).
lung adenocarcinoma (1 paper, 2022). A carcinoma that arises from the lung and is characterized by the presence of malignant glandular epithelial cells. "In this study, we continue to focus on the germline mutation of genes in lung adenocarcinoma and we have identified seven different variants (SMG5, RAB3GAF2, EI24, XDH, PTPRA, ATR, GSTZ1) in three sibling patients suffering from lung cancer." (PMID 35712480, 2022).
lymph node metastasis (1 paper, 2020). "Meanwhile, high EI24 protein expression inversely linked to tumor size, T stage, lymph node metastasis, and AJCC stage." (PMID 32974192, 2020). "Chi-square assessment posited that elevated EI24 protein expression was negatively linked to tumor size, American Joint Committee on Cancer (AJCC) stage, T stage, and lymph node metastasis and not linked to the patient’s age, gender, and pathological grade." (PMID 32974192, 2020).
metastatic tumors (1 paper, 2013). "Similar EI24 gene expression patterns were observed in metastatic tumors from various types of cancers." (PMID 24280371, 2013).
pancreatic ductal adenocarcinoma (1 paper, 2018). An infiltrating adenocarcinoma that arises from the epithelial cells of the pancreas. "In the present study, we found that EI24 was downregulated in pancreatic ductal adenocarcinoma (PDAC) tissues compared with adjacent normal tissues and was associated with cancer cell differentiation." (PMID 30369947, 2018).
prostate carcinoma (1 paper, 2019). A carcinoma that arises from epithelial cells of the prostate gland. "EI24 has been identified as an etoposide-inducible transcript and as a tumor suppressor inducing apoptosis in breast, cervical and prostate cancer cells." (PMID 31396480, 2019). "EI24 acts as a tumor suppressor in cervical, breast, and prostate cancers." (PMID 31396480, 2019).
skin cancer (1 paper, 2019). "They suggested that EI24 acts as a tumor suppressor in skin cancer." (PMID 31396480, 2019).
tumor (21 papers, 2007 to 2025). "Decreased expression levels of EI24 in epithelial tumor cells induced EMT in association with increased cell motility and invasiveness and resistance to anoikis." (PMID 24280371, 2013). "Indeed, by querying the public TCGA USC sequencing data, we found that the top coding-gene associated with CHK1 was EI24, a putative tumour suppressor gene, whose reduced expression has been associated with the induction of EMT and tumour progression." (PMID 33754208, 2021). "We speculated that these missense mutations might disrupt the function of EI24 in tubular ER formation, thus impairing apoptosis upon genome instability, which could allow tumor formation." (PMID 30030520, 2018). "In addition, other uncharacterized mechanisms underlying the regulation of EI24 in miR-455-3p-mediated tumor progression remains to be clarified." (PMID 28038450, 2017). "In addition, Caspase 2 and Ei24 act as tumor suppressor genes, and their loss may contribute to tumor metastasis." (PMID 28794853, 2017). "Furthermore, EI24 copy number loss correlated with high tumor grade in IDC and ILC." (PMID 24280371, 2013). "Of note, while EI24 has been controversially studied for being a tumor suppressor or promoter, its function in metabolic reprogramming is not known elsewhere." (PMID 40253325, 2025). "We further clarified that EI24 acts as a tumor suppressor in PDAC cell lines by inhibiting cell proliferation, decreasing colony formation, and inducing cell cycle arrest." (PMID 30369947, 2018). "We first examined the levels of EI24 mRNA in 6 pairs of tumor tissues and adjacent normal tissues resected from PDAC patients using qRT-PCR analysis." (PMID 30369947, 2018). "In contrast, other studies reported that reduced EI24 expression attenuated DMBATPA-induced skin carcinogenesis, suggesting a potential role for EI24 in tumor promotion." (PMID 30369947, 2018). "The results identified an elevation of EI24 mRNA levels by approximately 2.24-fold in the tumor tissues compared with the adjacent normal tissues in 4/6 (66.67%) of the samples (P < 0.05)." (PMID 30369947, 2018). "This indicates that c-Myc is an important target of EI24 and essential to its role as a tumor suppressor." (PMID 30369947, 2018). "More studies are required to verify the functional interaction between EI24 and c-Myc and to investigate other molecular targets and mechanisms for EI24 to clarify its role in tumor initiation and progression." (PMID 30369947, 2018). "Reduced expression of EI24 was found to be associated with the induction of epithelial-to-mesenchymal transition (EMT) and tumor progression by suppressing NF-κB activity." (PMID 28038450, 2017). "The risk allele of rs2059614 was associated with increased expression of EI24 and CHEK1 in normal breast epithelium adjacent to tumor from the METABRIC study (P = .002 and .007, respectively) (available online)." (PMID 25890600, 2015). "In this study, we demonstrated that the reduced expression of a single gene, EI24, results in the acquisition of systemic traits that strongly favor tumor progression." (PMID 24280371, 2013). "The multifaceted functions of EI24 in processes required for tumor malignancy make this gene an attractive candidate for therapeutic intervention." (PMID 24280371, 2013). "Collectively, these data support the notion that reduced expression of EI24 promotes tumor malignancy in vitro and in vivo." (PMID 24280371, 2013). "Based on these observations, we conclude that EI24 inhibits transcriptional activities required for execution of the EMT program in malignant tumor cells." (PMID 24280371, 2013).